MAPK15 (mitogen-activated protein kinase 15)
Diseases named in the same sentence as MAPK15 in open-access papers (continued):
Sharing a sentence is not in itself a finding about the gene and the disease.
osteosarcoma (3 papers, 2023 to 2025). A usually aggressive malignant bone-forming mesenchymal neoplasm, predominantly affecting adolescents and young adults. "Moreover, MAPK15 is indicated to be an osteosarcoma metastasis-associated gene, and is confirmed to promote the proliferation, migration, and invasion by activating the c-Jun/MMP signaling pathways." (PMID 38203280, 2023). "Evidence from previous studies suggests that MAPK15 facilitates osteosarcoma invasion cell migration via modulation of MMP-9 expression." (PMID 39866235, 2025).
ovarian carcinoma (3 papers, 2016 to 2023). A malignant neoplasm originating from the surface ovarian epithelium. "Taken together, our results indicate that a decreased MAPK15 expression is associated with advanced-stage ovarian cancer and unfavorable survival outcomes." (PMID 38203280, 2023). "MAPK15 deficiency is also involved in advanced stages through increasing tumor size and lymph node metastasis in ovarian cancer, which suggests that MAPK15 closely participates in tumor development." (PMID 38203280, 2023). "MAPK15 deficiency is associated with advanced-stage ovarian cancer and unfavorable survival outcomes." (PMID 38203280, 2023). "Here, we found a deficiency of MAPK15 expression in poorly differentiated ovarian carcinomas, which suggests that MAPK15 plays a pivotal role in the carcinogenesis of ovarian cancer." (PMID 38203280, 2023). "The low-expression groups comprised a higher ratio of elderly patients, poorly differentiated tumors, and advanced stage, suggesting that MAPK15 expression is involved in the carcinogenesis and progression of ovarian cancer." (PMID 38203280, 2023). "These correlations suggest that MAPK15 participates in ovarian cancer progression though affecting tumor growth and metastasis." (PMID 38203280, 2023). "In order to investigate the MAPK15 expression level in ovarian carcinoma, we performed IHC staining with MAPK15 antibody." (PMID 38203280, 2023). "The prognostic value of MAPK15 in ovarian cancer patients was assessed using the Kaplan-Meier Plotter database and Gene Expression Omnibus (GEO) datasets." (PMID 38203280, 2023). "In our study, we demonstrate MAPK15 is a novel biomarker capable of predicting the outcome of ovarian cancer, and as a contributor to cisplatin-related chemotherapy." (PMID 38203280, 2023). "This study aimed to explore for the first time on the relationship between MAPK15 expression and cancer progression/drug responsiveness in ovarian carcinoma." (PMID 38203280, 2023). "It would be valuable to further investigate the molecular mechanism of MAPK15 regulation in ovarian carcinoma." (PMID 38203280, 2023). "In conclusion, we have found that MAPK15 expression prolongs ovarian cancer patient survival through regulating cancer progression and enhancing chemotherapy effectiveness." (PMID 38203280, 2023). "The IHC results showed that MAPK15 expression was negatively associated with tumor grade, TNM stage, tumor size, and regional lymph node metastasis of ovarian carcinoma." (PMID 38203280, 2023). "In the present study, for the first time, we characterize the relationship of MAPK15 with clinicopathological parameters and prognostic outcomes in ovarian cancer." (PMID 38203280, 2023). "Consistently, survival analyses indicated MAPK15 is a favorable factor for the prognosis of ovarian cancer patients." (PMID 38203280, 2023). "It has been reported that the expression of MAPK15, NF-κB1 (p50), and NF-κB2 (p52) were obviously decreased in ovarian cancer cell lines, which indicate there are correlations between MAPK15 and the NF-κB family." (PMID 36900191, 2023). "The NF-kB1, NF-kB2 and MAPK15 genes expression were obviously decreased in ovarian cancer cell lines with dominant negative IkBαM." (PMID 27484466, 2016). "MAPK15 expression was negatively correlated with tumor grade (p = 0.0243), tumor size (p = 0.0236), regional lymph node metastasis (p = 0.0348), and tumor stage (p = 0.0046) of ovarian cancer." (PMID 38203280, 2023). "MAPK15 may be a new biomarker for ovarian cancer, and the encouraging therapeutic strategy would be found by combining the regulation of MAPK15 expression." (PMID 38203280, 2023). "Since MAPK15 clearly impacts ovarian cancer development and chemotherapy, we proposed a hypothesis that MAPK15 expression could be an indicator of ovarian cancer patient survival." (PMID 38203280, 2023). "Noteworthy, our results demonstrate that MAPK15 expression could enhance cisplatin cytotoxicity in ovarian cancer cells." (PMID 38203280, 2023).
ovarian carcinoma (continued). "Importantly, overexpressing MAPK15 increased cisplatin toxicity in ovarian carcinoma cells and online database analysis indicated that patients with high MAPK15 expression had favorable prognosis with/without chemotherapy." (PMID 38203280, 2023).
adenoma (2 papers, 2015 to 2022). A neoplasm arising from the epithelium. "Seven (44%) of the 16 patients with MAPK15 overexpression have the overexpression in concurrent adenoma and carcinoma lesions." (PMID 26035356, 2015). "MAPK15 overexpression was found in 2% of normal tissues, 21% of adenoma, and 37% of carcinoma tissues." (PMID 26035356, 2015). "MAPK15 overexpression was found in 1 (2%) of 44 normal regions, 8 (21%) of 38 adenomas and in 14 (37%) of 38 carcinoma regions." (PMID 26035356, 2015). "The overexpression of MAPK15 occurred at a high frequency in carcinomas (37%) compared to concurrent normal tissues (2%) and adenomas (21%)." (PMID 26035356, 2015). "Seven (44%) of the 16 patients have MAPK15 overexpression in concurrent adenoma and carcinoma lesions, and 7 (44%) have MAPK15 overexpression only in carcinoma lesions." (PMID 26035356, 2015).
embryonal carcinoma (2 papers, 2016 to 2020). A non-seminomatous malignant germ cell tumor characterized by the presence of large germ cells with abundant cytoplasm resembling epithelial cells, geographic necrosis, high mitotic activity, and pseudoglandular and pseudopapillary structures formation. "In the present study, we found that MAPK15 is overexpressed in specific subsets of GCT, i.e. seminomas and embryonal carcinomas (EC)." (PMID 26988910, 2016). "Here, we show a positive correlation between MAPK15 (ERK8; ERK7) expression and specific GCT subtypes, with the highest levels found in the aggressive embryonal carcinomas (EC)." (PMID 26988910, 2016). "Indeed, MAPK15 was not detectable in non-malignant teratoma areas, was moderately expressed in the seminoma component, whereas was highly expressed in the malignant embryonal carcinoma (EC) component." (PMID 26988910, 2016).
lung NET (2 papers, 2020 to 2023). "Our findings in the tumoral tissues, as well as the in vitro experiments with ZKK multi-kinase inhibitors, suggest that inhibition of IGF1R and MAPK15 could also be potentially effective in lung NET treatment." (PMID 33138224, 2020).
lymph node metastasis (2 papers, 2023 to 2025). "As compared to squamous cell carcinoma, we revealed that the expression of MAPK15 is relatively higher in adenocarcinoma and is associated with lymph node metastasis (p = 0.013)." (PMID 36900191, 2023). "Taken together, we show that a novel atypical MAPK and NF-κB subunit interaction promotes LUAD cell migration through transcriptional regulation of EP3, and higher MAPK15 level is associated with lymph node metastasis in patients with LUAD." (PMID 36900191, 2023). "Here, the expression of MAPK15 in LUAD was detected by immunohistochemistry and its correlation with clinical parameters such as lymph node metastasis and clinical stage was analyzed." (PMID 36900191, 2023). "The expression of MAPK15 is higher in patients with lymph node metastasis (N1 + N2) as compared to patients without lymph node metastasis (N0)." (PMID 36900191, 2023).
medulloblastoma (2 papers, 2021 to 2025). A malignant, invasive embryonal neoplasm arising from the cerebellum. "The aim of this study was to evaluate the role of MAPK15 in regulating Hedgehog signaling in medulloblastoma cells." (PMID 34638386, 2021). "MAPK15 regulates initial ciliogenesis in medulloblastoma cells, controlling hedgehog signaling." (PMID 39866235, 2025). "Specifically, medullo-spheres derived from these cells, an established in vitro model for evaluating progression and malignancy of putative tumor-initiating medulloblastoma cells, were used to demonstrate that MAPK15 regulates self-renewal of these cancer stem cell-like cells." (PMID 34638386, 2021). "In eukaryotes, MAPK15 controls the assembly of primary cilia, which are microtubule-based cell surface organelles necessary for sensing and processing developmental signals as well as for transducing tumorigenic Hedgehog signaling in medulloblastomas and basal cell carcinomas." (PMID 34638386, 2021). "Next, we took advantage of transformed human medulloblastoma cells belonging to the SHH-driven subtype, i.e., DAOY and ONS-76 cells, to ascertain the role for MAPK15 in HH-mediated cellular transformation." (PMID 34638386, 2021). "Specifically, interfering with MAPK15 functions reduces HH signaling and assembly of primary cilia both in immortalized NIH3T3 mouse fibroblasts and in transformed human medulloblastoma cells belonging to the SHH-driven subtype." (PMID 34638386, 2021).
nasopharyngeal carcinoma (2 papers, 2018 to 2021). A carcinoma arising from the nasopharyngeal epithelium. "At last, the MAPK15 has been reported to be a regulator for redioresistance in nasopharyngeal carcinoma cells, which is tightly linked to the Epstein-Barr virus (EBV) infection, which may relate to the EBV subtype of STAD." (PMID 34567063, 2021).
non-small cell lung carcinoma (2 papers, 2020 to 2023). A group of at least three distinct histological types of lung cancer, including non-small cell squamous cell carcinoma, adenocarcinoma, and large cell carcinoma. "Our previous research revealed that MAPK15 promotes metastasis via its interaction with NF-κB subunit p50 and the transcriptional regulation of prostaglandin E2 receptor EP3 subtype in human non-small cell lung cancer (NSCLC)." (PMID 38203280, 2023).
viral infection (2 papers, 2018 to 2025). "Several immune related DEGs (FADD, MAPK15, and GUCY1A2) in Fayoumi at 2 dpi, had been previously identified to be important in the host response to viral infection and the inflammatory response in cell lines." (PMID 30208883, 2018). "In fact, cells lacking MAPK15 expression are able to promptly respond to poly I:C, a stimulus that mimics viral infection." (PMID 40507959, 2025).
autoimmune disorders (1 paper, 2025). "Understanding the MAPK15 role in regulating IFNB1 and inflammation helps clarify how this pathway can be targeted to manage inflammatory and autoimmune disorders." (PMID 40507959, 2025).
carcinoid (1 paper, 2020). "MAPK15 expression was also detected by immunohistochemical staining in an atypical carcinoid." (PMID 33138224, 2020).
lung neoplasm (1 paper, 2020). A benign or malignant, primary or metastatic neoplasm involving the lungs. "The role of MAPK15 in carcinogenesis, including lung neoplasms, remains relatively understudied and ambiguous." (PMID 33138224, 2020).
neuroblastoma (1 paper, 2020). Neuroblastoma (NB) is the most common solid, extracranial childhood tumor. "Neuroblastoma is a malignancy of embryonal origin and upregulation of MAPK15 would be expected to facilitate tumor progression and indicative of aggressive disease and poor survival as in the SS group." (PMID 33245713, 2020).
Obesity (1 paper, 2021). Accumulation of substantial excess body fat. "The human ortholog of ERK7, MAPK15, is associated with obesity." (PMID 33369866, 2021).
Rett syndrome (1 paper, 2014). A severe neurodevelopmental disorder affecting the central nervous system.
seminoma (1 paper, 2016). A radiosensitive malignant germ cell tumor found in the testis (especially undescended), and extragonadal sites (anterior mediastinum and pineal gland). "In particular, we are currently interested in understanding whether MAPK15 may act downstream the KIT receptor tyrosine kinase, whose mutation at codon 816 is found in seminomas." (PMID 26988910, 2016).
small cell lung carcinoma (1 paper, 2020). Small cell lung cancer (SCLC) is a highly aggressive malignant neoplasm, accounting for 10-15% of lung cancer cases, characterized byrapid growth, and early metastasis. "In addition, the SCLC (small cell lung carcinoma) patients demonstrated higher mRNA levels of IGF1R (p = 0.010) and MAPK15 (p = 0.040) than the other BP-NEN groups." (PMID 33138224, 2020).
cancer (26 papers, 2013 to 2025). A tumor composed of atypical neoplastic, often pleomorphic cells that invade other tissues. "Mitogen-activated protein kinase 15 (MAPK15) has been reported to be associated with several cancers." (PMID 38203280, 2023). "To further investigate whether MAPK15 also has an effect on cancer chemotherapy, we measured the chemotherapy susceptibility of ovarian cell lines with altered MAPK15 expression." (PMID 38203280, 2023). "MAPK15 works as a key player of GalNAc-transferase relocalization to regulate cell migratory ability, and the loss of MAPK15 could make cancer cells more aggressive." (PMID 38203280, 2023). "According to the previous findings, the restoration of the telomeres in cancer cells depends on the presence of MAPK15 and occurs in a kinase-dependent manner." (PMID 39329988, 2024). "Heteromerizing with the subunit p50 of the transcriptional factor NFκB (nuclear factor κ-light-chain-enhancer of activated B cells) in cancer cells, MAPK15 translocates to the nucleus." (PMID 39329988, 2024). "Recent studies show that MAPK15 is involved in tumorigenesis and the progression of several cancers through regulating tumor development, distant metastasis, and drug susceptibility." (PMID 38203280, 2023). "As a kinase, MAPK15 carries out different functions in various cancers, indicating the deregulation of key pathways." (PMID 36900191, 2023). "Recent study reported the association of MAPK15 with BCR-ABL mediated autophagy and its role in oncogene dependent cancer cell proliferation and progression." (PMID 34441816, 2021). "Among the 148 dark kinases included in our analysis, PKMYT1 (in 17 cancers), Mitogen-Activated Protein Kinase 15 (MAPK15) in nine cancers, CaM Kinase Like Vesicle Associated (CAMKV) in 8 cancers), PNCK and STK31 (in seven cancers) were commonly upregulated." (PMID 33801837, 2021). "In the different locations, MAPK15 controls several important cellular functions, which are often related to the management of cell stress and to cancer development." (PMID 34638386, 2021). "Eight understudied kinases were found to have hotspot mutations in at least one cancer (CDC42BPA, DYRK1B, DYRK4, LMTK3, MAPK15, NEK7, TSSK1B, and TTBK1), with DYRK4, LMTK3, MAPK15, and NEK7 all having significant hotspot mutations in STAD." (PMID 33205077, 2020). "As an important cancer-related MAP kinase, MAPK15 regulates cellular function in cancer cells through multiple mechanisms." (PMID 30524968, 2018). "Amplification of 8q24.21, containing MYC locus, shows high frequency in cancer and this locus is close to 8q24.3, which contains the MAPK15 gene." (PMID 26035356, 2015). "The relationship between MAPK15 overexpression in 38 carcinoma lesions with clinicopathological characteristics was analyzed." (PMID 26035356, 2015). "However, the expression and regulation of MAPK15 are still unexplored in many other types of cancer." (PMID 38203280, 2023). "Indeed, we also show that interfering for MAPK15 expression strongly reduces the ability of an activated form of SMO to support cancer stem cells self-renewal, while failing to affect the same activity induced by the GLI2 oncogene." (PMID 34638386, 2021). "Based on the increased expression of MAPK15 in the cancer stem cell-enriched population of MB, we next evaluated whether the kinase was involved in regulating self-renewal of putative MB-initiating cells." (PMID 34638386, 2021). "Functional abnormality of MAPK15 is frequently seen in cancer initiation and progression." (PMID 30524968, 2018).
cancer (continued). "Although additional work will be necessary to clarify the role of MAPK15 in ECs, we clearly show that MAPK15 overexpression increases tumorigenicity of human tumor-derived cells and that its depletion is sufficient to constrain cancer cell proliferation and tumor formation in this system." (PMID 26988910, 2016). "All these data suggest that MAPK15 may play an important role in the development of human cancer and is an attractive target for cancer therapy." (PMID 26035356, 2015). "And, patients with copy number gain of MAPK15 in normal or premalignant tissues of stomach may have a chance to progress to invasive cancer." (PMID 26035356, 2015). "Notably, MAPK15 has been found to enhance cisplatin toxicity in various cancer cells and may be a potential therapeutic target, whereas the interactions between other model genes and cisplatin sensitivity are yet to be fully clarified." (PMID 40746884, 2025). "Also, we show that MAPK15 regulates self-renewal of MB stem cell-like cells, suggesting that inhibition of this kinase may reduce the MB cancer stem cell compartment, possibly diminishing the malignant potential of these tumors." (PMID 34638386, 2021). "MAPK15, the latest identified member of the MAPK family, is recognized for its upregulation across various cancer types." (PMID 39866235, 2025). "Our data show that MAPK15 knock-down reduces canonical HH signaling and inhibits proliferation of SHH-driven MB cell lines and generation of cancer stem cells." (PMID 34638386, 2021). "In cancer cells, fusion proteins, like BCR-ABL, can directly phosphorylate MAPK15." (PMID 39329988, 2024). "The role of MAPK15 and UBC in tumorigenesis has been reported in many previously discussed scientific works, while SMIM28 is a less studied gene with an unclear role in cancer." (PMID 33245713, 2020). "In the present study, we revealed that MAPK15 is more highly expressed in the tissues of LUAD patients with lymph node metastasis, and MAPK15 interacts with p50 to promote EP3 expression at the transcriptional level, thereby enhancing cancer cell migration and metastasis." (PMID 36900191, 2023). "Hence, the activation of the identified DEGs (MAPK4, MAPK15, and MAPK8IP3) might trigger the MAPK pathway and thereby influence drug resistance during cancer therapy." (PMID 37415453, 2023).